HNRNPR (heterogeneous nuclear ribonucleoprotein R)
Description:
Component of ribonucleosomes, which are complexes of at least 20 other different heterogeneous nuclear ribonucleoproteins (hnRNP). hnRNP play an important role in processing of precursor mRNA in the nucleus.
Synonyms: HNRPR; hnRNP-R; NEDDFSB
Tractability: PROTAC: UniProt records ubiquitination sites on it; ubiquitination databases record sites on it; its protein half-life has been measured.
Gene: Protein-coding gene on chromosome 1 (23,303,771 to 23,344,358, reverse strand). Ensembl gene ENSG00000125944.
Subcellular location: Nucleus; Microsome; Nucleus, nucleoplasm; Cytoplasm
Subcellular location (Human Protein Atlas): Nucleoplasm
Pathways (Reactome):
Metabolism of RNA: Processing of Capped Intron-Containing Pre-mRNA; mRNA Polyadenylation; mRNA Splicing - Major Pathway
Disease: Dengue Virus-Host Interactions
Gene Ontology:
Molecular function: protein binding; RNA binding; mRNA binding; nucleic acid binding
Biological process: mRNA processing; mRNA splicing, via spliceosome
Cellular component: catalytic step 2 spliceosome; cytoplasm; nucleolus; nucleoplasm; nucleus; ribonucleoprotein complex; spliceosomal complex
Genetic constraint (gnomAD): Loss-of-function variants: 2 observed, 48.8 expected, observed/expected ratio (o/e) 0.041, 90% interval 0.016 to 0.13. The upper end of that interval is the gene's LOEUF score, 0.13, which puts it in group 1 of 6, group 1 being the genes least tolerant of losing a copy. Missense variants: 346 observed, 622.91 expected, observed/expected ratio (o/e) 0.56, 90% interval 0.51 to 0.61. Synonymous variants: 180 observed, 210.42 expected, observed/expected ratio (o/e) 0.86, 90% interval 0.76 to 0.97.
Gene-disease validity (ClinGen):
ClinGen rates the evidence that HNRNPR causes each of these diseases.
syndromic intellectual disability (autosomal dominant): Definitive. A intellectual disability that is part of a larger syndrome.
Homologues: Orthologues: chimpanzee HNRNPR (100% identical), dog HNRNPR (100% identical), macaque HNRNPR (100% identical), guinea pig HNRNPR (99% identical), pig HNRNPR (99% identical), rabbit HNRNPR (99% identical), mouse Hnrnpr (99% identical), rat Hnrnpr (99% identical), zebrafish hnrnpr (85% identical), rat Hnrnpr-ps2 (79% identical), tropical clawed frog hnrnpr (72% identical). Paralogues in human: SYNCRIP (82% identical), PABPC4 (16% identical), PABPC1 (15% identical), PABPC3 (15% identical), RBMS1 (14% identical), PABPC1L (14% identical), RBMS2 (14% identical), RBMS3 (14% identical), SF3B4 (12% identical), ELAVL2 (12% identical), ELAVL4 (12% identical), PUF60 (12% identical), and 12 more.
Diseases named in the same sentence as HNRNPR in open-access papers:
HNRNPR is named in the same sentence as 41 diseases in open-access papers, as found by Europe PMC text mining. Sharing a sentence is not in itself a finding about the gene and the disease. The quoted sentences say what the papers report.
gastric cancer (6 papers, 2019 to 2025). A primary or metastatic malignant neoplasm involving the stomach. "HNRNPR, a member of the spliceosome C complex, has been reported to have oncogenic role in human tumors, and mediate the metastasis of gastric cancer and hepatocellular carcinoma." (PMID 41347062, 2025). "During the development of gastric cancer, hnRNPR overexpression can promote the cancer cell survival and metastasis." (PMID 35875075, 2022). "HNRNPR contributes to the proliferation and metastasis of gastric cancer, whereby HNRNPR hypomethylation leads to tumor proliferation and metastasis." (PMID 36438661, 2022). "HnRNPR was reported as a pro-oncogene in gastric cancer development and promoted the transcription of the c-fos oncogene." (PMID 35875075, 2022). "Although the role of many hnRNP family members in different human cancers has been reported, little is known about the role of hnRNPR in tumors, particularly in gastric cancer." (PMID 31527303, 2019). "The endogenous expression status of hnRNPR in five gastric cancer cell lines (SGC-7901, AGS, HGC-27, MKN-28, MGC-803) and one normal epithelial cell line GES-1 was examined." (PMID 31527303, 2019). "Additionally, qRT‐PCR examination revealed a significant upregulation of hnRNPR in gastric cancer tissues (n = 40)." (PMID 37867401, 2023). "First, we assessed whether the mRNA level of hnRNPR is overexpressed in pan-cancers, including gastric cancer." (PMID 31527303, 2019). "Similarly, high hnRNPU levels are also observed in gastric cancer tissues and predict poor prognosis in gastric cancer patients, suggesting that hnRNPR and hnRNPU may be tumor-promoting factors in gastric cancer cells." (PMID 35875075, 2022). "The results of flow cytometry also showed that hnRNPR promoted G2/M transition phase of the cell cycle by upregulation CCNB1, These findings indicated that hnRNPR enhanced the cell proliferation of gastric cancer cells via maintaining CCNB1 stability." (PMID 31527303, 2019).
infertile (2 papers, 2025 to 2026). "In this study, we reveal a previously unrecognized role of hnRNPR in male germ cell development and infertility." (PMID 41436426, 2025). "Here, we identified pathogenic mutations in HNRNPR from three infertile patients whose partners repeatedly failed to achieve transferable embryos despite undergoing both in vitro fertilization (IVF) and intracytoplasmic sperm injection (ICSI)." (PMID 41618099, 2026).
lung carcinoma (2 papers, 2022 to 2025). "The HNRNPA2B1 levels were positively associated with TARDBP (R = 0.83), DHX9 (R = 0.73), HNRNPR (R = 0.77), SRSF1 (R = 0.79), HNRNPD (R = 0.75), and HNRNPM (R = 0.78) genes in lung cancer (all P < 0.001)." (PMID 35529270, 2022).
male infertility (2 papers, 2025 to 2026). The inability of the male to effect fertilization of an ovum after a specified period of unprotected intercourse. "Collectively, these findings reveal a previously unrecognized molecular mechanism by which HNRNPR mutations cause sperm-borne oocyte activation failure and male infertility, while highlighting targeted therapeutic strategies to restore fertilization." (PMID 41618099, 2026). "Pathogenic mutations in HNRNPR cause sperm motility decline, morphological abnormality, and male infertility in both humans and mice." (PMID 41436426, 2025). "In conclusion, our study identifies hnRNPR as a key regulator of spermiogenesis in humans and mice, and a novel genetic determinant of male infertility." (PMID 41436426, 2025). "To estimate the therapeutic effect of mEVs-SKAP2 on male infertility, we carried on mEVs-SKAP2 trial on human semen samples derived from three groups: normal population, individuals harboring HNRNPR mutations and patients diagnosed with idiopathic asthenoteratozoospermia." (PMID 41436426, 2025). "Altogether, these findings identify hnRNPR as a pivotal regulator of m6A-mediated Skap2 splicing during spermiogenesis and highlight extracellular vesicle SKAP2 as a promising therapeutic target for poor sperm quality and male infertility." (PMID 41436426, 2025).
neuroblastoma (2 papers, 2018 to 2025). Neuroblastoma (NB) is the most common solid, extracranial childhood tumor. "Studies have shown that hnRNPR and hnRNPA2B1 bind to and stabilize ASCL1 mRNA in a m6A-dependent manner, thereby promoting the progression of neuroblastoma." (PMID 40344709, 2025).
cecum adenocarcinoma (1 paper, 2022). "In Kaiser’s dataset, hnRNPR was overexpressed in the colorectal adenocarcinoma types compared with that in the normal samples (COAD with fold change = 1.386, rectosigmoid adenocarcinoma with fold change = 1.688, and cecum adenocarcinoma with fold change = 1.436)." (PMID 35875075, 2022).
cholangiocarcinoma (1 paper, 2019). A carcinoma that arises from the intrahepatic biliary tree (intrahepatic cholangiocarcinoma) or from the junction, or adjacent to the junction, of the right and left hepatic ducts (hilar cholangiocarcinoma). "Notably, hnRNPR was also upregulated in many cancers, including cholangiocarcinoma, Lymphoid neoplasm diffuse large B-cell lymphoma, Glioblastoma multiforme, bran lower grade glioma, pancreatic adenocarcinoma, and thymoma." (PMID 31527303, 2019).
colorectal adenocarcinoma (1 paper, 2022). The most common type of colorectal carcinoma. "Collectively, high expressions of hnRNPA1, hnRNPK, hnRNPR, and hnRNPU were significantly associated with better OS rates for colorectal adenocarcinoma patients." (PMID 35875075, 2022). "Furthermore, we demonstrated that high expressions of hnRNPA1, hnRNPK, hnRNPR, and hnRNPU were associated with better overall survival rates for colorectal adenocarcinoma patients." (PMID 35875075, 2022). "Our data first demonstrated that high expression of hnRNPR existed in colorectal adenocarcinoma and predicted increased OS rates, indicating that hnRNPR is a prognostic biomarker for human colorectal adenocarcinoma." (PMID 35875075, 2022). "Immunohistochemical staining revealed that hnRNPA1, hnRNPA2B1, hnRNPC, hnRNPK, hnRNPR, and hnRNPU are overexpressed in colorectal adenocarcinoma." (PMID 35875075, 2022). "The results showed that hnRNPA1, hnRNPK, hnRNPR, and hnRNPU in the nucleus had higher expressions in colorectal adenocarcinoma cells compared with FHC cells." (PMID 35875075, 2022). "By using IHC staining of 10 human colorectal adenocarcinoma specimens, we confirmed that hnRNPA1, hnRNPA2B1, hnRNPC, hnRNPK, hnRNPR, and hnRNPU were mainly localized in the nucleus and had higher expressions in colorectal adenocarcinoma tissues compared with adjacent normal tissues (ANT)." (PMID 35875075, 2022).
cutaneous melanoma (1 paper, 2022). A primary melanoma arising from atypical melanocytes in the skin. "After correcting for multiple testing, the only significant promoters were TERT in cutaneous melanoma and pan-cancer; BCL7A, IGLL5, BCL2, and POLR3E pan-cancer; and HNRNPR in uterine adenocarcinoma." (PMID 36396655, 2022).
esophageal cancer (1 paper, 2022). A primary or metastatic malignant neoplasm involving the esophagus. "The Oncomine, TCGA, and GEO datasets were used to investigate HNRNPR expression in the pan- and esophageal cancers, as well as its relationship with N6-methyladenosine (m6A) modification and glycolysis." (PMID 36195940, 2022).
Fanconi anemia (1 paper, 2022). Fanconi anemia (FA) is a hereditary DNA repair disorder characterized by progressive pancytopenia with bone marrow failure, variable congenital malformations and predisposition to develop hematological or solid tumors. "Fanconi Anemia has been associated with an increased risk of ESCA, and GASE analysis revealed that HNRNPR may participate in the Fannie anemia pathway, which complements the important role of HNRNPR in ESCA." (PMID 36195940, 2022).
Growth delay (1 paper, 2021). A deficiency or slowing down of growth pre- and postnatally. "A subset of probands have growth delay (30.5%, n = 61/200), particularly probands with variation in HNRNPH1 (62.5%, n = 5/8), HNRNPH2 (47.8%, n = 11/23), HNRNPR (90%, n = 9/10, significantly more so than HNRNPK probands [p = 0.03]), and HNRNPUL2 (50%, n = 3/6)." (PMID 33874999, 2021).
HNRNPU-related disorder (1 paper, 2021). "HNRNPU-related disorder probands with LGD variants also exhibit stereotypy (21.7%, n = 15/69, mostly recurrent hand flapping), as do HNRNPR-related disorder probands (33.3%, n = 3/9)." (PMID 33874999, 2021).
leukemia (1 paper, 2019). A malignant (clonal) hematologic disorder, involving hematopoietic stem cells and characterized by the presence of primitive or atypical myeloid or lymphoid cells in the bone marrow and the blood. "In our study, the transcription level of HNRNPR in leukemia cells was significantly increased after treatment with nsPEF, suggesting that the nsPEF may affect the immune differentiation of Jurkat cells." (PMID 31766457, 2019). "To further explore the clinical significance of these hub genes (SUGP1, DHX16, FUS, HNRNPR, DHX15, NAA38, SKIV2L2, and PLRG1), we used a series of online tools to evaluate the clinical expression of these hub genes in leukemia." (PMID 31766457, 2019).
microcephaly (1 paper, 2021). A congenital or acquired developmental disorder in which the circumference of the head is smaller than normal for the person's age and sex. "In addition to ASD, variants in probands with speech delay or microcephaly and HNRNPR variants are clustered (p = 0.005 and p = 0.001, respectively)." (PMID 33874999, 2021).
spinal muscular atrophy (1 paper, 2019). A motor neuron disease that affect the muscles, and characterized by muscle weakness and atrophy resulting from progressive degeneration and irreversible loss of the anterior horn cells in the spinal cord (i.e., lower motor neurons) and the brain stem nuclei. "In addition, we surveyed the LC domains of other members in the hnRNP family, including hnRNPA2, hnRNPDL, hnRNPH, hnRNPK, and hnRNPR, which were identified to be closely associated with different diseases, such as ALS, spinal muscular atrophy (SMA), and cancer." (PMID 31043593, 2019).
T-cell acute lymphoblastic leukemia (1 paper, 2019). Acute lymphoblastic leukemia of T-cell origin. "The mRNA expression of HNRNPR in T-cell acute lymphoblastic leukemia was higher than in bone marrow." (PMID 31766457, 2019).
cancer (11 papers, 2019 to 2025). A tumor composed of atypical neoplastic, often pleomorphic cells that invade other tissues. "HNRNPR is highly expressed in the majority of pan-cancers, including ESCA, and is associated with BMI, weight, and history of reflux in patients with ESCA." (PMID 36195940, 2022). "We then found that the most significant DEGs were tightly associated with progression of cancers, including PTMA, HNRNPR, RAPH1, TRAF3IP1, CNBP, and PRR15." (PMID 41347062, 2025). "Further analysis revealed that the mRNA level of HNRNPR was increased in many cancers, including ESCA." (PMID 36195940, 2022). "Increasing evidence indicates that HNRNPR and its family have garnered considerable interest and have been identified as cancer biomarkers." (PMID 36195940, 2022). "Currently, eight hnRNPs members (hnRNPA1, hnRNPA2B1, hnRNPC, hnRNPD, hnRNPF, hnRNPK, hnRNPR, and hnRNPU) seem to be more relevant to cancer development, according to reported literature." (PMID 35875075, 2022). "The analysis of ESCA patient data from the TCGA and GEO database revealed that HNRNPR expression was significantly elevated in cancer tissue than in normal tissue or para-cancerous tissue." (PMID 36195940, 2022). "We analyzed the transcription level of HNRNPR in various pan-cancer and normal individuals using the Oncomine online database and TCGA dataset." (PMID 36195940, 2022). "Collectively, these results demonstrated that hnRNPR functions as an oncogene in GC and directly controls the fate of cancer cells and their metastasis." (PMID 31527303, 2019). "In addition, overexpression of some genes, including ABCB1, TPD52L1, HNRNPR and MICAL3, is associated with poor prognosis in various cancers." (PMID 39682186, 2024). "As a hnRNPs homologous gene, HNRNPR is structurally and functionally comparable to other members of this family and considered to have the ability to act as a proto-oncogene in numerous cancers." (PMID 36195940, 2022). "Additionally, research of the Oncomine online database and the TCGA dataset revealed that HNRNPR expression was significantly increased in the majority of pan-cancers, including ESCA." (PMID 36195940, 2022). "The interaction between HNRNPR and a variety of proteins indicates that HNRNPR may have the ability to act like other cancer proto-oncogenes." (PMID 36195940, 2022). "Results showed that HNRNPR expression level was higher level in many cancers than in normal tissue." (PMID 36195940, 2022). "Functionally, hnRNPR promoted cancer cell proliferation, migration, and invasion." (PMID 31527303, 2019). "In tumor migration, hnRNPR directly interacts with CCNB1 and CENPF mRNA to contribute to tumor malignancy and poor outcomes in cancer patients." (PMID 37479693, 2023). "Thus, we attempted to establish whether hnRNPR interacts with other targets in cancer metastasis." (PMID 31527303, 2019). "While HNRNPR has not been extensively investigated in cancer, the significance of its co-family genes in a variety of cancers has been gradually discovered." (PMID 36195940, 2022). "Currently, the function of hnRNPR and the molecular mechanisms in cancer progression are not known." (PMID 31527303, 2019).
tumor (7 papers, 2019 to 2026). "HNRNPR expression is altered in many malignancies, suggesting that it is associated with tumor formation." (PMID 36091765, 2022). "Significant ilQTLs, the majority of which of somatic origin, were identified in immune-relevant genes, including B2M, HLA genes, CANX, LDHA, PSMB2, and HNRNPR, which are known to affect the tumor immune landscape." (PMID 38773080, 2024). "HNRNPR and its co-family genes are highly correlated with many aspects of tumor therapy, such as m6A modification and targeted glycolytic pathway." (PMID 36195940, 2022). "The hnRNPR-positive cells or MMP9 positive areas in shhnRNPR tumor were remarkably reduced than those in the control tumors." (PMID 31527303, 2019). "The analysis of hnRNPR expression ratio in tumor/non-tumor matched tissues revealed that the expression of hnRNPR was significantly increased in GC." (PMID 31527303, 2019). "Using the subcutaneous in vivo model, it was observed that hnRNPR markedly slowed the tumor proliferation rate and impaired tumor growth, this was consistent with the finding that hnRNPR acted as an oncogene in vitro." (PMID 31527303, 2019). "Knockdown of hnRNPR in two type mice models, with two types of tumors models decreased the tumor aggressiveness and metastasis." (PMID 31527303, 2019). "Based on liver metastasis model created by intra-spleen injection, it was found that hnRNPR knockdown decreased the number of metastatic nodules and tumor size." (PMID 31527303, 2019). "High expression of hnRNPR in GC strongly correlates with tumor aggressiveness." (PMID 31527303, 2019). "Furthermore, the protein level of hnRNPR in the tumor was positively correlated with the expression of CCNB1 and CENPF in clinical samples." (PMID 31527303, 2019). "Additionally, there were experiments demonstrated that overexpression of HNRNPR in GC significantly accelerated the process of cell cycle and promoted tumor cell proliferation and invasion, indicating that HNRNPR works as a pro-oncogene in the occurrence and development of GC." (PMID 36195940, 2022). "The oncogenic activity of hnRNPR was dependent on its ability to stabilize the mRNA of CCNB1 and CENPF, which are key mediators of cell cycle and tumor metastasis, respectively." (PMID 31527303, 2019). "hnRNPR stabilizes CCNB1 and CENPF mRNA to promote tumor metastasis." (PMID 37479693, 2023). "Therefore, we hypothesize that HNRNPR may promote ESCA by modifying m6A-related genes, hence affecting the level of tumor methylation, and eventually resulting in ESCA progression." (PMID 36195940, 2022).
HNRNPR also shares sentences with these, for which no sentence is quoted: epilepsy (2 papers); hepatocellular carcinoma (2); neurodegenerative disease (2); amyotrophic lateral sclerosis (1); breast carcinoma (1); colon cancer (1); developmental delay (1); diffuse large B-cell lymphoma (1); frontotemporal dementia (1); gastric tumor (1); Glioblastoma multiforme (1); glioma (1); hereditary leiomyomatosis (1); lymph node metastases (1); lymphoid neoplasm (1); Obesity (1); pancreatic adenocarcinoma (1); rectosigmoid adenocarcinoma (1); speech delay (1); stomach adenocarcinoma (1); thymoma (1); triple-negative breast carcinoma (1).